ATF4 (activating transcription factor 4)
Diseases named in the same sentence as ATF4 in open-access papers (continued):
Sharing a sentence is not in itself a finding about the gene and the disease.
Mitochondrial myopathy (5 papers, 2017 to 2023). "In mitochondrial myopathy muscle, mTORC1-activated ATF4 regulates the mitochondrial stress response." (PMID 37793777, 2023). "ATF4 has been considered an important transcription factor in mitochondrial myopathy in mice and humans and in the mouse heart depleted of FXN." (PMID 35531957, 2022). "Noteworthy, a recent study uncovered the mechanistic target of rapamycin complex 1 (mTORC1) as key regulator of muscle ATF4-mediated ISRmt and that treatment with rapamycin (mTORC1 inhibitor) reversed progression of mitochondrial myopathy in Deletor mice." (PMID 29402993, 2018). "Inhibition of mTORC1 with rapamycin was recently demonstrated to slow the progression of mitochondrial myopathy in mouse models by improving several hallmarks of mitochondrial dysfunction, resulting in reduced expression of Atf4, Fgf21, mitochondrial chaperones and key enzymes of the 1C pathway." (PMID 29132502, 2017). "A stress response involving ATF4 has previously been observed in both C10S59L and C2/C10-DKO mice (as well as in other mitochondrial myopathy models), although the mechanism for this response in vivo has not been elucidated." (PMID 35700042, 2022).
nasopharyngeal carcinoma (5 papers, 2017 to 2023). A carcinoma arising from the nasopharyngeal epithelium. "We have reported the upregulation of two ER stress proteins, activating transcription factor 4 (ATF4) and stanniocalcin (STC2), in response to non-thermal plasma exposure of CNE-1, a radiation-resistant nasopharyngeal cancer cell line." (PMID 28467380, 2017).
Osteopenia (5 papers, 2021 to 2025). Osteopenia is a term to define bone density that is not normal but also not as low as osteoporosis. "Atf4 regulates osteogenesis through its ability to regulate Ocn and collagen type I. Deletion of Atf4 in mice led to impaired terminal osteoblast differentiation and resulted in severe osteopenia and other defects during skeletal development." (PMID 34539793, 2021). "Mice lacking ATF4 (Atf4−/−) exhibit osteopenia and significantly reduced collagen synthesis by osteoblasts." (PMID 40774385, 2025).
periodontitis (5 papers, 2021 to 2023). An acute or chronic inflammatory process that affects the tissues that surround and support the teeth. "The results showed that 4-PBA could downregulate the expression levels of ER stress-associated genes GRP78, PERK, ATF4, and CHOP in periodontitis-related inflammation." (PMID 33763140, 2021). "TRPA1 inhibitor inhibits endoplasmic reticulum stress by downregulating the PERK/eIF2α/ATF-4/CHOP pathway and reducing oxidative stress and apoptosis in periodontitis mice, thereby improving periodontitis." (PMID 36875034, 2023). "TRPA1 was highly related to periodontitis, and TRPA1 inhibitor significantly reduced oxidative and apoptotic levels in inflammatory PDLCs via inhibiting ER stress by downregulating PERK/eIF2α/ATF-4/CHOP pathways." (PMID 35720191, 2022). "Our previous studies demonstrated that unfolded protein accumulation in the ER activates the canonical unfolded protein response (UPR) representative genes including GRP78, PERK, ATF4, and CHOP and subsequently results in ER stress response, which may facilitate the aggravation of periodontitis." (PMID 33763140, 2021).
anemia (4 papers, 2014 to 2024). A reduction in the number of red blood cells, the amount of hemoglobin, and/or the volume of packed red blood cells. "Also, ATF4 null mice suffer from a variety of defects including anemia, bone dysgenesis, and micropthalmia that complicate experimental design and interpretation." (PMID 25071442, 2014). "However, although ATF4 is required to inhibit mTORC1 signalling, ATF4−/− mice develop microcytic hypochromic anaemia, unlike HRI−/− mice." (PMID 31729420, 2019).
breast invasive carcinoma (4 papers, 2018 to 2021). "To examine the clinical relevance of HER2, ATF4, and ZEB1, we analyzed the expression of these genes in invasive breast carcinoma using TCGA databases." (PMID 31064130, 2019).
clear cell renal cell carcinoma (4 papers, 2018 to 2025). "We also recently reported that ATF4 mRNA levels are much higher in human clear cell renal cell carcinoma patient specimens than in normal kidney samples." (PMID 37569418, 2023).
Cognitive impairment (4 papers, 2020 to 2025). Abnormal cognition is characterized by deficits in thinking, reasoning, or remembering. "Evidence suggests that PERK is directly responsible for cognitive impairment in AD patients, and both the activation of PERK and ATF4 expression have been shown to impair the transcriptional activity of CREB, leading to synaptic plasticity inhibition." (PMID 32754028, 2020).
depression (4 papers, 2015 to 2025). "Activating transcription factor 4 (ATF4), a transcription factor acting downstream of GCN2, has important roles in synaptic plasticity and memory, both of which are implicated in depression development." (PMID 39872511, 2023). "However, there are no direct effects of GCN2-eIF2α-ATF4 in the regulation of depression-like behaviors." (PMID 39872511, 2023).
diabetic cardiomyopathy (4 papers, 2013 to 2026). Diabetic cardiomyopathy is a disorder of the heart muscle in people with diabetes. "(2020a) revealed that the differentially expressed genes between treated and untreated samples were mostly enriched in the metabolic process and cell cycle-related process, and further identified ATF4 as a novel prognostic biomarker of diabetic cardiomyopathy." (PMID 41561820, 2026). "(2023) showed that ATF4 expression was significantly increased in the hearts of mice with diabetic cardiomyopathy, and deletion of ATF4 improved cardiac dysfunction through inhibiting oxidative stress, reducing cardiomyocyte apoptosis and alleviating cardiac fibrosis in diabetic mice." (PMID 41561820, 2026). "Empagliflozin has also been found to induce a protective effect against diabetic cardiomyopathy by inhibiting IRE1a-Xbp1 and ATF4-CHOP pathways, whilst it can also improve β-cell mass in streptozotocin-treated mice through down-regulation of Xbp1, BiP and ATF4." (PMID 33467546, 2021). "For instance, ATF4 in DCM promotes cardiac fibrosis and oxidative stress, while downregulation of Bmal1 induces mitochondrial dysfunction by promoting Bcl2/IP3R-mediated mitochondrial Ca2+ overload, leading to diabetic cardiomyopathy." (PMID 38664790, 2024).
diabetic retinopathy (4 papers, 2014 to 2023). "Moreover, pentazocine upregulates PERK, activating transcription factor 4 (ATF4), ATF6, IRE1, and the C/EBP Homologous Protein (CHOP) expression in experimental models of diabetic retinopathy." (PMID 36768323, 2023). "In addition, our recent studies have shown that ER stress and the PERK/eIF2α/ATF4/CHOP pathway are involved in regulation of immune response and retinal vascular injury in diabetic retinopathy, a common complication of diabetes." (PMID 25914608, 2015). "Taken together, our results suggest a critical role of ATF4 in the regulation of MCP-1 production in retinal and brain microvascular endothelial cells, which may contribute to inflammation-related endothelial injury in diseases such as diabetic retinopathy." (PMID 25914608, 2015).
hypertriglyceridemia (4 papers, 2014 to 2023). A laboratory test result indicating elevated triglyceride concentration in the blood. "Furthermore, ATF4-deficient mice show reductions in hypertriglyceridemia induced by high fructose diets and increased insulin sensitivity, suggesting that ATF4 may act as a modulator of lipid metabolism in the liver." (PMID 25156122, 2014). "Hence, the authors concluded that ATF4 deficiency decreased hepatic lipogenesis but did not affect TG secretion and FA oxidation, thus protecting Atf4‐deficient mice from fructose‐induced hepatic hypertriglyceridemia." (PMID 33398919, 2021).
inflammatory bowel disease (4 papers, 2018 to 2024). A spectrum of small and large bowel inflammatory diseases of unknown etiology. "ATF4 is a stress-induced transcription factor whose expression has been correlated with degree of intestinal inflammation and development of inflammatory bowel diseases in adults." (PMID 29312822, 2018). "A study indicated that the expression of ATF4 was decreased in inflamed intestinal mucosa of patients with active inflammatory bowel diseases, and overexpression of ATF4 down-regulated inflammatory factors including IL-1β and IL-6, while deprivation of ATF4 promotes intestinal inflammation." (PMID 38913045, 2024).
liver disease (4 papers, 2021 to 2025). "PERK-eIF2α-ATF4-CHOP signaling in the UPR pathway is implicated in liver diseases." (PMID 34689832, 2021). "The PERK/ATF4/CHOP signaling pathway plays a key role in ER stress-induced liver disease." (PMID 40183095, 2025). "Adult cholestatic liver disease samples had similar trends of the IRE1α/XBP1 and p-eIf2α -ATF4 expression suggesting that the UPR changes in the cholestatic liver groups may not be restricted to pediatric populations." (PMID 36520816, 2022). "Finally, adult cholestatic liver disease samples had similar trends of the IRE1α/XBP1 and p-eIf2α -ATF4 expression suggesting that the UPR changes in the cholestatic liver groups may not be restricted to pediatric populations." (PMID 36520816, 2022).
muscle atrophy (4 papers, 2017 to 2025). The loss of muscle tissue due to inactivity or disease. "Together, these results identify a biochemical mechanism by which ATF4 induces skeletal muscle atrophy, providing molecular-level insights into the etiology of skeletal muscle atrophy." (PMID 31953319, 2020).
myocardial infarction (4 papers, 2016 to 2025). Gross necrosis of the myocardium, as a result of interruption of the blood supply to the area, as in coronary thrombosis. "This study extends previous findings indicating that upregulation of P2X7R during myocardial infarction activates the Nox4/PERK/ATF4 pathway, which is known to regulate HIF-1α and VEGF." (PMID 41295364, 2025). "In the setting of acute myocardial infarction, pre‐treatment with guanabenz (which enhances eIF2α phosphorylation and increases ATF4 levels) largely corrected the deficit in Nox4 KO hearts but had no additional effect in WT hearts." (PMID 26742780, 2016).
myocardial ischemia (4 papers, 2021 to 2023). A disorder of cardiac function caused by insufficient blood flow to the muscle tissue of the heart. "The m6A methyltransferase WTAP increases ER stress by regulating m6A modification of ATF4 mRNA, thus promoting myocardial ischemia/reperfusion injury." (PMID 37378749, 2023). "Berberine (200 mg/kg/day, for 2 weeks) suppressed myocardial ischemia/reperfusion-injury induced ER stress by reducing the phosphorylation of PERK and eIF2α and decreasing the expression of ATF4 and CHOP in hearts of male rats." (PMID 35615361, 2022).
myopia (4 papers, 2015 to 2025). "Real-time PCR and Western blotting were performed to detect the expression of GRP78, p-eIF2α, spliced XBP1, ATF6, ATF4 and p-IRE1α in the lenses of normal human subjects and patients with age-related, myopia-related or congenital cataracts." (PMID 26091066, 2015). "Additionally, regulatory transcriptional factors, such as Cdx2 in the small intestines and Atf4 in the liver — both are involved in hypoxia pathway — were activated in myopia." (PMID 41330940, 2025). "In the lenses of the age-related and high myopia-related cataract groups, the protein levels of ATF6, p-eIF2α and p-IRE1α and the gene expression levels of spliced XBP1, GRP78, ATF6 and ATF4 were greatly increased." (PMID 26091066, 2015).
nutritional deficiency (4 papers, 2022). "To further investigate the role of the ATF4 gene in NPCs under nutritional deficiency, we used the siRNA-induced gene knockout method to knock out the ATF4 gene in NPCs." (PMID 36324122, 2022). "The CCK8 assay suggested that the ATF4 gene knockout can reduce cell viability under nutritional deficiency by using 1% serum-containing media." (PMID 36324122, 2022). "Our findings revealed that PKM2 inhibition reduced the cell apoptosis induced by ATF4 silence under nutritional deficiency by inhibiting AKT phosphate." (PMID 36324122, 2022). "Our findings revealed that PKM2 inhibition reduces the cell apoptosis induced by ATF4 silence under nutritional deficiency by inhibiting AKT phosphate." (PMID 36324122, 2022). "The results suggested the ATF4 gene knockout can increase cell apoptosis under nutritional deficiency by using 1% serum-containing media." (PMID 36324122, 2022). "Consistent with this, HIF-1α was reduced in the PKM2 inhibition group under nutritional deficiency, and PKM2 inhibition can reduce the HIF-1a level induced by ATF4 silence under nutritional deficiency." (PMID 36324122, 2022). "Namely, PKM2 inhibition reduces the cell apoptosis induced by ATF4 silence under nutritional deficiency via inhibiting AKT phosphate." (PMID 36324122, 2022). "Interestingly, the overexpression of PKM2 in NPCs with an ATF4 mutation can reduce cell apoptosis and reduce the phosphatidylinositol-AKT induced by the ATF4 mutation under nutritional deficiency." (PMID 36324122, 2022). "Moreover, we found that PKM2 inhibition can reduce the cell apoptosis induced by ATF4 silence under nutritional deficiency." (PMID 36324122, 2022). "However, PKM2 inhibition can increase cell apoptosis after ATF4 silence under nutritional deficiency." (PMID 36324122, 2022). "KM2 inhibition can increase AKT phosphate after ATF4 silence under nutritional deficiency." (PMID 36324122, 2022). "This suggests that PKM2 may function downstream of ATF4 during NPC apoptosis induced by nutritional deficiency." (PMID 36324122, 2022). "The apoptosis caused by nutritional deficiency may be brought about by affecting ATF4- or PKM2-induced cell energy metabolism." (PMID 36324122, 2022). "In addition, we found that PKM2 inhibition can reduce the cell apoptosis induced by ATF4 silence under nutritional deficiency." (PMID 36324122, 2022). "However, PKM2 inhibition can decrease cell viability after ATF4 silence under nutritional deficiency." (PMID 36324122, 2022). "However, with the aggravation of nutritional deficiency caused by ATF4 knockdown, severe autophagy was induced, which may promote apoptosis." (PMID 35864117, 2022). "ATF4 is related to the reduction of stress in cancer cells due to lipid accumulation and malnutrition, as well as angiogenesis and metastasis, and conversely, when the situation changes, cancer cells are vulnerable to apoptosis through chemotherapy." (PMID 35356209, 2022). "This is the first study to investigate the relationship between ATF4 and PKM2 in NPC apoptosis under nutritional deficiency." (PMID 36324122, 2022). "What is more, PKM2 inhibition can reduce the NP cells’ glucose uptake and lactic acid level induced by ATF4 silence under nutritional deficiency, indicating that PKM2 is downstream of ATF4." (PMID 36324122, 2022).
pancreatic adenocarcinoma (4 papers, 2019 to 2025). "Importantly, analysis of patients with cutaneous melanoma and patients with pancreatic adenocarcinoma showed that ATF4-dependent transcriptional signatures correlated with collagen I, CAF markers and overall survival." (PMID 35654839, 2022). "Notably, Hpa2 overexpression itself in pancreatic adenocarcinoma cell lines induced expression of the ER stress response proteins Bip, CHOP, and activating transcription factor 4 (ATF4)." (PMID 39910799, 2025).
pancreatic ductal adenocarcinoma (4 papers, 2022 to 2025). An infiltrating adenocarcinoma that arises from the epithelial cells of the pancreas. "Furthermore, activating transcription factor 4 (ATF4) reportedly upregulated expression of heat-shock 70kDa protein 5 (HSPA5) in pancreatic ductal adenocarcinoma." (PMID 36158661, 2022). "This study focused on improving the gemcitabine sensitivity in pancreatic ductal adenocarcinoma (PDAC) by targeting ATF4/HSPA5/GPX4 axis, while the exact molecular mechanism was not deeply studied." (PMID 40603306, 2025).
renal cell carcinoma (4 papers, 2023 to 2025). "PDIA4 inhibits ferroptosis in renal cell carcinoma through the PERK/ATF4/SLC7A11 signaling pathway." (PMID 39544949, 2024).
sarcopenia (4 papers, 2017 to 2025). Progressive decline in muscle mass due to aging which results in decreased functional capacity of muscles. "After establishing a connection between ER stress and characteristics of sarcopenia, we determined whether the impact of CPNE1 overexpression on mitochondrial function in young satellite cells was influenced by the PERK/eIF2α/ATF4 pathway, which is associated with ER stress and the UPR." (PMID 36525128, 2023).
tauopathy (4 papers, 2017 to 2025). Neurodegenerative disorders involving deposition of abnormal tau protein isoforms (tau proteins) in neurons and glial cells in the brain. "Recently, it was reported that ATF4 and phosphorylated (p) tauThr212/Ser214 levels were reduced in rTg4510 tauopathy mice by chronic administration of trazodone (40 mg/kg/d corresponding to 194 mg/d in humans." (PMID 35273086, 2022). "Because the three stress transducers of the UPRER each control transcriptional regulation via XBP1s, ATF6n, and ATF4 transcription factors, understanding the role of downstream upregulated target genes is important for identifying unique regulators of tauopathy." (PMID 39060347, 2024). "The present study aimed to investigate the involvement of ER stress in AD-like outcomes in vitro, as measured by ATF4 and CHOP, and in vivo using experimental AD models of tauopathy (MAPT P301S) and excessive amyloidosis (APPSwe)." (PMID 28721361, 2017).
type 2 diabetes (4 papers, 2017 to 2025). "In adipocyte 2, transcription factors associated with neurodegenerative diseases, type 2 diabetes, and cancer (Ctcfl, Etv3, Atf4, Zmiz1, Sp3) showed reduced activity in the old group." (PMID 40631796, 2025). "One of the potential compounds that regulate ATF4 expression is Exendin-4 (Exenatide), the first glucagon-like peptide 1 receptor agonist used clinically as a therapeutic agent for type 2 diabetes." (PMID 34547510, 2021). "Based on these results, we hypothesized that induction of apoptosis and/or alteration of ATF4 activity might be involved in the changes in the brains of OLETF rats at different stages of type 2 diabetes." (PMID 34506507, 2021). "It is possible that increased ATF4 expression without induction of apoptosis in the brain is one of the pathological features of type 2 diabetes already found at the prediabetic stage." (PMID 34506507, 2021).
ulcerative colitis (4 papers, 2022 to 2024). An inflammatory bowel disease involving the mucosal surface of the large intestine and rectum. "The primary intent of this manuscript is to ascertain the effect of cucurbitacin IIa on ulcerative colitis (UC) and illustrate the potential mechanisms based on intestinal barrier function and the PERK/ATF4/CHOP signaling pathway." (PMID 39763247, 2024). "Western blotting and RT-PCR showed that the PERK/eIF2α/ATF4/CHOP pathway was activated in colon tissue of model mice, suggesting that the pathway is involved in the pathogenesis of ulcerative colitis (UC) and could become a potential therapeutic target." (PMID 35186102, 2022).
acute lymphoblastic leukemia (3 papers, 2021). Leukemia with an acute onset, characterized by the presence of lymphoblasts in the bone marrow and the peripheral blood. "Mechanistically, sHA 14-1 induces a rapid ER Ca2+ release that triggered the expression of ER stress-associated transcription factor ATF4/CREB-2 and apoptosis in B cell acute lymphoblastic leukemia (B-ALL) cell lines." (PMID 33407740, 2021). "According to the previous reports, GSK-J4 inhibits lipopolysaccharide-induced TNFα production in human primary macrophages with IC50 of 9 μM21 and blocks growth of T cell acute lymphoblastic leukemia (T-ALL) cells with IC50 of 2 μM, indicating that GSK-J4 is a highly potent inducer of ATF4 and CHOP." (PMID 33633164, 2021).